NEK2 (NIMA related kinase 2)
Diseases named in the same sentence as NEK2 in open-access papers (continued):
Sharing a sentence is not in itself a finding about the gene and the disease.
pancreatic cancer (20 papers, 2012 to 2025). "Collectively, the results demonstrate that NEK2 inhibition suppressed the onset and development of pancreatic cancer, possibly associated with the decreased expression of PD-L1." (PMID 34315872, 2021). "In conclusion, NEK2 is a prognostic factor of immunologically “hot” and low mutational pancreatic cancer." (PMID 34315872, 2021). "The results demonstrated that the T193/209A mutation in PD-L1 reduced its expression but the T193/209D mutation increased its expression in pancreatic cancer cells, while the K37R mutation in NEK2 caused its loss of regulatory effect on the expression and phosphorylation of PD-L1." (PMID 34315872, 2021). "A high level of NEK2 was also associated with a poor prognosis in pancreatic cancer." (PMID 33221765, 2020). "In pancreatic cancer, NEK2 can enhance its stability through phosphorylation of PD-L1, and inhibition of NEK2 can increase lymphocyte infiltration in tumor tissue, enhance anti-tumor immune response and sensitivity to immunotherapy." (PMID 38503948, 2025). "NIMA-related kinase 2 (NEK2) stabilizes PD-L1 by phosphorylating threonine 194 (T194) and threonine 210 (T210), especially in pancreatic cancer, preventing degradation by the UPS." (PMID 40087690, 2025). "For example, in pancreatic cancer, NEK2 can inhibit ubiquitination-proteasome degradation by binding to PD-L1 and phosphorylating its T194/T210 sites." (PMID 38503948, 2025). "Targeting NEK2 with specific inhibitors has shown promising results in preclinical studies, particularly for gastric and pancreatic cancers." (PMID 40076620, 2025). "This stabilisation undermines the efficacy of PD-L1-targeted immunotherapy and exacerbates the immunosuppressive microenvironment in pancreatic cancer, while targeting NEK2 can enhance anti-pancreatic cancer immune responses." (PMID 41463025, 2025). "Because NEK2 plays a pivotal role in the immune response of pancreatic cancer, NEK2 inhibitors can alleviate the immune resistance of this cancer type 36." (PMID 38706902, 2024). "The simultaneous inhibition of NEK2 and PD-L1 was found to significantly inhibit the development of pancreatic cancer in a preclinical model." (PMID 36612193, 2022). "Based on these findings, the present study further demonstrated that NEK2 is a critical regulator of PD-L1 phosphorylation, and is involved in tumorigenesis and the progression of pancreatic cancer." (PMID 34315872, 2021). "NEK2 inhibition thereby sensitizes PD-L1 blockade, synergically enhancing the anti-pancreatic cancer immune response." (PMID 34315872, 2021). "Taken together, the results indicate a positive correlation and direct interaction of NEK2 with PD-L1 inside the ER lumen in pancreatic cancer." (PMID 34315872, 2021). "Given the considerable influence of the tumor immune microenvironment on immune checkpoint blockade (ICB) therapy, we investigated the prognostic roles of NEK2 in pancreatic cancers with different immune statuses." (PMID 34315872, 2021). "Taken together, the results suggest that NEK2 is involved in the development and progression of PDAC in an immune-dependent manner, with deletion of NEK2 improving pancreatic cancer immunogenicity." (PMID 34315872, 2021). "Combinatorial inhibition of NEK2 and PD-L1 significantly improves therapeutic efficacy in pancreatic cancer in preclinical models." (PMID 34884892, 2021). "Inhibition of NEK2 thereby sensitizes PD-L1 blockade and synergistically enhances the immune response against pancreatic cancer." (PMID 34884892, 2021). "NEK2 interacts with and phosphorylates PD-L1 at the T194/T210 residues, maintaining its stability, and thus inhibition of NEK2 leads to expedited degradation of PD-L1, activating cytotoxic T cells to obliterate pancreatic cancer cells." (PMID 34315872, 2021). "Taken together, NEK2 was found to be a prognostic factor in immunologically “hot” pancreatic cancer." (PMID 34315872, 2021).
pancreatic cancer (continued). "In this work, we demonstrate that PD-L1 is a substrate of NEK2, and combinatorial inhibition of NEK2 and PD-L1 largely improves the therapeutic efficacy of pancreatic cancer in preclinical models." (PMID 34315872, 2021). "NEK2 inhibition or depletion decreased PD-L1 expression in pancreatic cancer cells, while the overexpression of NEK2 induced the upregulation of PD-L1." (PMID 34315872, 2021). "We identify NEK2 as a prognostic factor in immunologically “hot” pancreatic cancer, involved in the onset and development of pancreatic tumors in an immune-dependent manner." (PMID 34315872, 2021). "Collectively, the results suggest that the NEK2 inhibitor enhanced the efficacy of PD-L1 blockade both in vitro and in vivo, alleviating immuno-resistance in pancreatic cancer." (PMID 34315872, 2021). "The depletion of NEK2 by siRNA was found to inhibit pancreatic cancer tumor growth in a xenograft mouse model." (PMID 32294979, 2020). "IGF2BP3 (p<0.0001), HOXB7 (p<0.0001), and NEK2 (p<0.0001) mRNA expression levels were significantly increased in patients with cholangiocarcinoma or pancreatic cancer." (PMID 22879911, 2012). "Additionally, given the critical role of tumor mutation burden (TMB) in the immunotherapy response, we next investigated the prognostic relevance of NEK2 in immunologically “hot” pancreatic cancer with high or low TMB, respectively." (PMID 34315872, 2021). "The combination of a NEK2 inhibitor and anti-PD-L1 antibody synergistically suppresses tumor growth both in vivo and in vitro, thus representing the potential for sensitizing PD-L1-targeted therapy in pancreatic cancer." (PMID 34315872, 2021). "Here the authors show that NEK2 controls the stability of PD-L1 by preventing its proteasome-mediated degradation and that NEK2 targeting restores anti-tumor immune responses in preclinical models of pancreatic cancer." (PMID 34315872, 2021). "A KPC-NEK2 knockdown (KD) pancreatic cancer cell line, stably transfected with Nek2 double nickase plasmids, was generated to determine whether NEK2 is associated with an anti-tumor immune response." (PMID 34315872, 2021). "Here, we demonstrate that never in mitosis gene A-related kinase 2 (NEK2) phosphorylates PD-L1 to maintain its stability, causing PD-L1-targeted pancreatic cancer immunotherapy to have poor efficacy." (PMID 34315872, 2021). "Consequently, while further preclinical studies and clinical trials are warranted for demonstration, NEK2 is nevertheless a promising target for pancreatic cancer therapy, and the combinatorial inhibition of NEK2 and PD-L1 will synergistically benefit pancreatic cancer patients." (PMID 34315872, 2021). "Furthermore, high expression of NEK2 was also found to be significantly associated with vascular invasion and tumor grade as opposed to TNM stage and other clinical indices in multiple patient cohorts of pancreatic cancer." (PMID 34315872, 2021). "Hence, NEK2 may be considered a therapeutic biomarker for ICB, and intervention with NEK2 may enhance the efficacy of PD-L1 blockade in “hot” pancreatic tumors." (PMID 34315872, 2021). "In contrast, the effect of the GSK3β inhibitor on NEK2 and PD-L1 expression was not very stable and significant in pancreatic cancer cells." (PMID 34315872, 2021).
cervical cancer (18 papers, 2013 to 2025). A primary or metastatic malignant neoplasm involving the cervix. "Recently, a study revealed an association between NEK2 and radioresistance in cervical cancer, showing its influence on cellular sensitivity to ionizing radiation (IR) by regulating DNA damage and apoptosis." (PMID 38783335, 2024). "To explore the underlying mechanisms that contribute to the effects of NEK2 in cervical cancer, we performed RNA sequencing (RNA-seq) to compare the genomic expression profiles of HeLa cells transfected with control or NEK2-targeting siRNAs." (PMID 32907622, 2020). "NEK2 was overexpressed in cervical cancer tissues and cell lines and was associated with tumor staging and lymph node metastasis in cervical cancer tissues; knocking down NEK2 inhibited the proliferation of cervical cancer and promoted the radiosensitivity of cervical cancer." (PMID 35733923, 2022). "Importantly, our rescue results showed that the biological effects caused by NEK2 knockdown are mainly dependent on Wnt1 in cervical cancer cells." (PMID 32907622, 2020). "To investigate whether Wnt1 is indeed required for the observed phenotypes caused by NEK2 silencing in cervical cancer cells, we transfected exogenously expressed Wnt1 into NEK2-depleted cells." (PMID 32907622, 2020). "In cervical cancer, NEK2 activates β-catenin signaling by promoting wnt1 expression, enhancing cell resistance to radiotherapy." (PMID 38503948, 2025). "The genetic knockout of the NEK2 gene accelerates DNA damage accumulation by impairing DNA repair mechanisms, thus ultimately enhancing radiosensitivity in cervical cancer cells." (PMID 38651153, 2024). "It is reported that the knockdown of NEK2 can reduce the expression of Wnt1 and β-catenin to subvert the oncogenesis of cervical cancer cells." (PMID 37986152, 2023). "Targeting NEK2 inhibits tumorigenesis through the Wnt1/beta-catenin signaling pathway in cervical cancer." (PMID 36499051, 2022). "We report that NEK2 protein level is overexpressed and correlated with the tumor stage and lymph node metastasis in cervical cancer tissues." (PMID 32907622, 2020). "NEK2 positivity was dramatically higher in cervical cancer tissues (70.7%) than in the adjacent paracarcinoma tissues (24.4%) (P < 0.001)." (PMID 32907622, 2020). "In our study, we demonstrate that NEK2 protein levels are significantly upregulated and that elevated expression of NEK2 is correlated with the tumor stage and lymph node metastasis in cervical cancer." (PMID 32907622, 2020). "Subsequent functional studies confirmed this notion that loss of NEK2 suppresses tumorigenesis in vitro and in vivo, indicating that NEK2 plays oncogenic role in cervical cancer." (PMID 32907622, 2020). "The percentage of γ-H2AX foci-positive cells was dramatically increased in NEK2-depleted cervical cancer cells after irradiation exposure." (PMID 32907622, 2020). "In this study, we report that NEK2 protein is overexpressed and correlated with the tumor stage and lymph node metastasis in cervical cancer tissues." (PMID 32907622, 2020). "Accordingly, our work uncovered that NEK2 is a novel positive modulator of Wnt1 and provided new insights into the molecular mechanisms by which NEK2 participates in oncogenesis and radioresistance in cervical cancer." (PMID 32907622, 2020). "As expected, NEK2 silencing suppressed the growth of cervical cancer cells compared with control cells." (PMID 32907622, 2020). "NEK2 knockdown amplifies DNA damage signal and impedes DNA repair, ultimately leading to enhanced radiosensitivity in cervical cancer." (PMID 32907622, 2020). "Accordingly, these results reveal that NEK2 exerts its biological functions mainly via regulating Wnt1 in cervical cancer." (PMID 32907622, 2020). "Collectively, our results support the notion that NEK2 promotes the radioresistance of cervical cancer cells." (PMID 32907622, 2020).
cervical cancer (continued). "Consistent with this notion, the 5-ethynyl-2′-deoxyuridine (EdU) staining assay showed that the proliferation of cervical cancer cells was inhibited when NEK2 was depleted." (PMID 32907622, 2020). "More importantly, the observed consequences induced by NEK2 depletion in cervical cancer cells can be partially rescued by Wnt1 overexpression." (PMID 32907622, 2020). "We detected the protein levels of NEK2 in cervical carcinoma tissues and paired paracarcinoma tissues by immunohistochemistry." (PMID 32907622, 2020). "NEK2 upregulation promotes radiation resistance in cervical cancer." (PMID 40072068, 2025). "Previous studies have shown that radiation‐induced DNA damage increases γ‐H2AX foci‐positive cells among NEK2‐inhibited cervical cancer cells and reduces the focal positivity of HR regulators involved in DNA repair, confirming that NEK2 knockdown accelerates DNA damage." (PMID 38426218, 2024). "More importantly, NEK2 could inactivate the Hippo signaling pathway, resulting in growth-promoting genes high expression in cervical cancer." (PMID 37233832, 2023). "Indeed, knockdown or inhibition of PLK1, CDK1, AURKA, MELK, and NEK2 resulted in reduction or repression of metastatic potential and invasiveness of various cancer types, including mCRPC and cervical cancer." (PMID 34680307, 2021). "Given that NEK2 is overexpressed and promotes radioresistance in cervical cancer, targeting NEK2 may be a desirable therapeutic strategy for cervical cancer radiotherapy." (PMID 32907622, 2020). "Our findings indicate that targeting NEK2/Wnt1/β-catenin pathway may be a potential radiosensitization strategy in cervical cancer." (PMID 32907622, 2020). "Nevertheless, the exact roles and underlying mechanisms of NEK2 in cervical cancer progression and radioresistance has not yet been investigated." (PMID 32907622, 2020). "To test this hypothesis, we first downregulated the expression level of NEK2 in two different cervical cancer cell lines (HeLa and SiHa) by siRNA transfection." (PMID 32907622, 2020). "To further validate whether NEK2 expression is indeed upregulated, we detected NEK2 protein level in 41 paraffin-embedded cervical cancer tissues and paired paracarcinoma tissues by immunohistochemistry." (PMID 32907622, 2020). "In our study, we identified Wnt1 as a key downstream effector of NEK2 in cervical cancer." (PMID 32907622, 2020). "Our results demonstrate that NEK2 activates the Wnt/β-catenin signaling pathway via Wnt1 to drive oncogenesis and radioresistance in cervical cancer, indicating that NEK2 may be a promising target for the radiosensitization of cervical cancer." (PMID 32907622, 2020). "Given that NEK2 is overexpressed in cervical cancer tissues, we speculated that it may act as an oncogenic protein in cervical cancer." (PMID 32907622, 2020). "Furthermore, we provided evidence that depletion of NEK2 impairs oncogenesis and enhances radiosensitivity in cervical cancer." (PMID 32907622, 2020). "Notably, a significant correlation was found between NEK2 expression and the tumor stage as well as lymph node metastasis in 123 paraffin-embedded cervical cancer tissues (P < 0.05)." (PMID 32907622, 2020). "Our clinical data demonstrated that NEK2 is overexpressed in cervical cancer and associated with the tumor stage and lymph node metastasis, indicating that NEK2 may act as an oncoprotein involved in cervical cancer tumorigenesis." (PMID 32907622, 2020). "Moreover, we for the first time show that NEK2 upregulates Wnt1 to activate Wnt/β-catenin signaling pathway, thereby promoting oncogenesis and radioresistance in cervical cancer." (PMID 32907622, 2020). "In addition, our expression analyses using Gene Expression Omnibus (GEO) data set GSE9750 revealed that the mRNA levels of NEK2 were higher in human cervical cancer cell lines than that in normal cervix epithelial cells." (PMID 32907622, 2020).
cervical cancer (continued). "However, few studies have examined the effects of NEK2 on tumor aggressiveness and radiotherapy resistance in cervical cancer." (PMID 32907622, 2020). "NEK2 was primarily localized in the nucleus and was overexpressed in cervical cancer tissues." (PMID 32907622, 2020). "Together, these results indicate that NEK2 upregulation may contribute to oncogenesis in cervical cancer." (PMID 32907622, 2020). "Importantly, we show that NEK2 depletion impairs cervical cancer progression and radioresistance in a Wnt1-dependent manner, indicating that NEK2 may be a promising target for cervical cancer radiotherapy." (PMID 32907622, 2020). "To elucidate whether NEK2 is related to this classical oncogenic pathway, we examined the expression of β-catenin and found that NEK2 silencing led to significant reduction in β-catenin at the protein level in two different cervical cancer cell lines." (PMID 32907622, 2020). "NEK2, a serine/threonine kinase involved in mitosis, has been found to function in chromosome instability, tumor progression and metastasis, but its role in cervical cancer radioresistance remains unknown." (PMID 32907622, 2020). "Notably, a recent study reported that the mRNA expression level of NEK2 is significantly higher in invasive cervical cancer than in normal tissue, indicating that NEK2 may serve as a tumor-promoting protein in cervical cancer." (PMID 32907622, 2020). "By upregulating WNT1 expression levels, NEK2 activates the WNT/β-catenin signaling pathway, which promotes cervical cancer development while also conferring radiation resistance." (PMID 38651153, 2024). "Interestingly, bioinformatics analysis with the TCGA database showed that there was a positive correlation between NEK2 and β-catenin mRNA expression in cervical cancer tissues, further suggesting that NEK2 may be a critical regulator of Wnt/β-catenin signaling in cervical cancer." (PMID 32907622, 2020). "Conversely, it is possible that one or more tumor suppressor genes (PAX7, FBG3, ARH1, NEK2, RGL and ARCH) located on chromosome-1 are involved in the development or progression of cervical cancer." (PMID 23429197, 2013). "Exploration of STRIPAK in cervical cancer has recently emerged, with a study proposing signalling between the never in mitosis gene A (NIMA)-related kinase 2 (NEK2) protein, working in parallel with the STRIPAK complex to dephosphorylate MST1/2 and activate YAP in the Hippo signalling pathway." (PMID 38201504, 2023). "In the present paper we identified six putative biomarkers (AURKA, DTL, HMGB3, KIF2C, NEK2, and RFC4) which should be further tested to separate indolent HPV related cervical infections from progressive CIN III lesions and for early diagnosis of cervical cancer." (PMID 26701206, 2016).